IGF1R (insulin like growth factor 1 receptor)
Diseases named in the same sentence as IGF1R in open-access papers (continued):
Sharing a sentence is not in itself a finding about the gene and the disease.
Hyperglycemia (89 papers, 2011 to 2025). An increased concentration of glucose in the blood. "Given that IGF-1R inhibitors can cause hyperglycemia, combining these with metformin, which has both hypoglycemic and anti-cancer effects, has shown superior therapeutic outcomes in BC cell lines." (PMID 39273251, 2024). "IGF-1R-targeted TKIs were limited by co-inhibition of IR-B, which regulates glucose uptake, and thus were associated with an increased risk of hyperglycaemia." (PMID 37308971, 2023). "First, in the clinical setting, IGF1R inhibition with IGF1R antagonist monoclonal antibodies or IGF tyrosine kinase inhibitor small molecules causes hyperglycemia and subsequent hyperinsulinemia due to cross-reactivity with the IRB and hybrid receptors." (PMID 33260481, 2020). "This is one likely cause for dose-limiting hyperglycemia in patients treated with IGF-1R antibody; other causes include the endocrine response to IGF-1R blockade, inducing hepatic secretion of GH and IGFBPs which can impair glucose tolerance." (PMID 31416218, 2019). "The objective of the current study was to evaluate if there are other post-transcriptional mechanism(s) mediated by miRNAs that regulate IGF1R expression post-burn injury which in turn causes hyperglycemia in patients with burn injury." (PMID 29069833, 2017). "What's more, we noticed that in some trials the IGF-1R antibodies were well tolerated whereas in others they caused more severe side effects including hyperglycemia and neutropenia." (PMID 28427155, 2017). "IGF1R-targeting therapies have been reported to cause various side effects, most commonly hyperglycemia, a hallmark of type 2 diabetes." (PMID 24434591, 2014). "However, they had no clinical activity in phase 3 trials in numerous cancers and caused the side effects of hyperglycemia along with hyperinsulinemia due to IGF-1R targeting." (PMID 37373357, 2023). "We observed that sustained hyperglycemia and hyperinsulinemia over 4 days was associated with increased proliferation, but whether these are effects are mediated through Igf1r function compensation will require double receptor gene knockout experiments." (PMID 35136059, 2022). "IGF-1R inhibition commonly causes hyperglycemia, which induces endogenous insulin secretion." (PMID 36556357, 2022). "Indeed, xentuzumab was associated with a low incidence of hyperglycaemia compared with anti-IGF-1R mAbs and TKIs." (PMID 32161368, 2020). "Several phase III clinical trials targeting IGF-1R with small molecule inhibitors have so far failed due to side effects such as hyperglycemia and metabolic syndrome caused by the homology of IGF-1R and insulin receptor (IR) and IGF elevation in response to disruption of glucose homeostasis." (PMID 32355893, 2019). "Therefore, peripartum hyperglycemia, which may reflect worse metabolic control during pregnancy, is associated to increased IGF-1R phosphorylation and increased expression of the IR-A isoform." (PMID 33776919, 2021). "Hyperglycaemia and insulin excess potentiate leptin-mediated signalling, particularly via IGF1R–Akt–mTOR activation, further accelerating cell cycle progression and biomass accumulation in breast and mammary epithelial cells." (PMID 41586225, 2025). "First of all, due to the involvement of the PI3K/Akt pathway in glycolysis, PI3K inhibition induces hyperglycemia, which activates insulin signaling, especially through the insulin-like growth factor 1 receptor (IGF1R)." (PMID 40647529, 2025). "Nonselective inhibition of the IR causes hyperglycemia, and inhibition of the insulin-like growth factor-1 receptor (IGF1R), which also contributes to glucose metabolism, commonly induces hyperglycemia in cancer clinical trials." (PMID 40303997, 2025). "Linsitinib is a dual inhibitor of IGF-1R and insulin receptor which brings concerns for potential side effects related to the induction of hyperglycemia, which was however only observed in less than 1% of patients." (PMID 39759002, 2024).
Hyperglycemia (continued). "In the development of T2D, Igf1r is found overexpressed or activated in response to hyperglycemia and hyperinsulinemia, leading to the deterioration of the disease." (PMID 38961143, 2024). "Given this, the targeted inhibition of IGF-1R can also lead to metabolic abnormalities, such as hyperglycemia and insulin dysregulation, through the action of IGF-1R/IR-A hybrids." (PMID 38540176, 2024). "The side effects of anti-IGF-1R therapy—hyperinsulinemia and hyperglycemia—warrant the further development of strategies to manage this toxicity." (PMID 37373357, 2023). "Nevertheless, the upregulation of IGF1R was observed followed by hyperglycemia and hyperinsulinemia, leading to deterioration of DM." (PMID 36891946, 2023). "IGF1R antibodies or inhibitors had been mainly developed for cancer treatment; however, nearly all of them failed owing to their side effects, such as hyperglycemia due to high sequence homology with the insulin receptor." (PMID 37717026, 2023). "Hyperinsulinemia and hyperglycemia are the most prominent pathophysiological features that play a key role in T2DM-induced colonic carcinogenesis through activating IGF-1R and RAGE, respectively." (PMID 35296101, 2022). "Despite the importance of IGF1R as an anti-cancer target, the clinical benefits of IGF1R inhibitors are still limited mainly due to hyperinsulinemia and hyperglycemia toxicity." (PMID 34067117, 2021). "Any further development of anti-IGF-1R therapy will require better control of anti-IGF-1R drug-induced hyperglycemia and the development of more predictive biomarkers." (PMID 34611148, 2021). "The IGF-1R antibody therapy resulted in hyperglycemia and metabolic syndrome, and the receptor tyrosine kinase inhibitors manifested metabolic toxicities, most likely due to high similarity between IGF-1R and insulin receptor." (PMID 30185144, 2018). "Our results indicate that increased let-7b suppressing IGF1R activation ultimately leads to inactivation of Gsk3β and concurrent activation of glycogen synthase leading to hyperglycemia." (PMID 29069833, 2017). "Our results show that the miRNA let-7b is robustly induced in burn injury and attenuates IGF1R protein expression and downstream activation of GSK3β that results in hyperglycemia." (PMID 29069833, 2017). "In vivo targeting of let-7b by antagomir mitigated the effect of increased let-7b expression on IGF1R protein expression and hyperglycemia." (PMID 29069833, 2017). "Collectively, hyperglycemia, hyperinsulinemia, and hyperlipidemia induced by the inhibition of IR and IGF1R improved after the withdrawal of OSI-906 treatment." (PMID 28646158, 2017). "More specifically, it has been shown that the miR-194 can target the insulin-like growth factor receptor 1 (IGF1R) and silence its protein expression resulting in hyperglycemia." (PMID 29069833, 2017). "First, insulin-like growth factor-1 receptor antibody therapy resulted in hyperglycemia and metabolic syndrome most likely due to disruption of insulin-like growth factor-1 homeostasis and subsequent growth hormone elevation." (PMID 29152592, 2017). "Previous study showed that IGF-1 can inhibit mesangial cell apoptosis and hyperglycemia-induced DNA damage and promote DNA repair via activating IGF-1R signaling." (PMID 26986757, 2016). "IGF-1R blocking therapy, however, is reported to be well-tolerated in clinical phase I and II trials with only 3 to 25% of participants developing hyperglycemia." (PMID 24809702, 2014). "Hyperglycemia has been attributed to insulin resistance secondary to high levels of growth hormone, a compensatory reaction to IGF-1R antibodies." (PMID 21729319, 2011). "The consequence of IGF-1R inhibition leads to compensatory increase of growth hormone stimulation that promotes liver gluconeogenesis, resulting in hyperglycemia." (PMID 21729319, 2011).
Hyperglycemia (continued). "The indirect impact on insulin receptor signaling might also play a role, as IGF-1R inhibitors block the insulin receptor, preventing insulin from binding to its receptor, thereby inhibiting cellular glucose uptake and leading to hyperglycemia." (PMID 40496563, 2025). "The therapeutic use of anti-IGF-2 neutralizing antibodies may offer better tolerability by avoiding hyperglycemia, a common side effect of small molecule IGF1R inhibitors, due to cross-reaction with the Insulin Receptor." (PMID 36809604, 2023). "Pro-hypertrophic IGF-1R/ERK1/2 pathway and hypertrophic marker expression were activated in miR-378a deficiency and upon STZ/HG treatment of miR-378a+/+ specimens in vivo and in vitro suggesting miR-378a-independent hyperglycemia-promoted hypertrophy." (PMID 37851320, 2023). "The present study aimed to evaluate both the content and activation of IR and IGF-1R in the placenta of T1D patients (having pre-pregnancy hyperglycemia) compared to GDM patients (having hyperglycemia initiated during pregnancy) and to women with normal glucose tolerance during pregnancy." (PMID 33776919, 2021). "The addition of a specific IRA inhibitor would be required to overcome this, as nonspecific IR inhibitors (e.g., the compound S961) and IGF1R tyrosine kinase inhibitor small molecules cause hyperglycemia and compensatory hyperinsulinemia." (PMID 33260481, 2020). "In contrast with the IGF1R antagonist monoclonal antibodies and IGF1R tyrosine kinase inhibitors, these compounds do not cause hyperglycemia, as they do not compromise insulin action." (PMID 33260481, 2020). "Accordingly, several IGF-1R inhibitors have reached different stages of anti-cancer clinical development; yet none have been approved for clinical application due to complications like hyperglycemia and hyperinsulinemia." (PMID 33291663, 2020). "For example, hyperglycemia is the most common side effects of anti-IGF-1R mAbs." (PMID 28427155, 2017). "The results revealed that it was much less potent than AZD9291 against both INSR (GI50: 2.8μM versus 0.5 μM) and IGF1R (GI50: 3.6 μM versus 0.56 μM) indicating that there was much less chance that this drug could induce the hyperglycemia adverse effects." (PMID 28407693, 2017). "We presumed here that hyperglycemia might abate InsR and IGF-1R expressions in the myenteric ChAT+ neurones but the detailed mechanism needs to be further clarified." (PMID 28931726, 2017). "Hyperglycemia is a known class effect of IGF-1R directed agents." (PMID 24905030, 2014). "Hyperglycemia is recognized as an adverse event of treatment with anti-IGF-1R antibodies." (PMID 23921573, 2013). "Consequently, targeting IGF-1R or its ligands may lead to unintended side effects, such as hyperglycemia, complicating patient management and limiting the dosage of therapies." (PMID 39273251, 2024). "This correlated with the pattern of pro-hypertrophic IGF-1R pathway activation in respective murine cardiac specimens as well as miR-378−/− hiPSC-CMs and HG-cultured miR-378a+/+ hiPSC-CMs that also showed increased size, and suggests miR-378a independent hyperglycemia-promoted hypertrophy." (PMID 37851320, 2023). "Moreover, IGF-1R blockade may result in many adverse effects, such as hyperglycemia and impaired glucose tolerance, which cannot be ignored in CRC patients with T2DM." (PMID 35296101, 2022). "In addition, due to their lack of specificity, IGF-1R tyrosine kinase inhibitors are associated with hyperglycemia because of interference with insulin signaling." (PMID 30692633, 2019). "Our results also indicate that topical insulin application in patients with burn injury might alleviate hyperglycemia in the short term but without causing an activation of IGF1R it might be difficult to sustain its beneficial activity." (PMID 29069833, 2017).
Hyperglycemia (continued). "Moreover, overexpression of decorin protected endothelial function from hyperglycemia and promoted angiogenesis through IGF1R/AKT/AP-1/VEGF signaling, suggesting that decorin could be a new therapeutic strategy for patients suffering from DCM." (PMID 28290552, 2017). "Finally, to the extent insulin can promote IR-A mediated oncogenic effects, one could hypothesize its use for the treatment of iatrogenic hyperglycemia should be avoided in patients harboring IGF-1R driven malignancies when other pharmacological options exist." (PMID 24212944, 2011). "Tyrosine kinase inhibitors (TKIs) such as linsitinib are able to inhibit IGF1R as well as the INSR, leading to toxicities from metabolic complications such as hyperglycemia." (PMID 30653502, 2019). "Cumulatively, this indicated that burn serum exposure can promote let-7b expression, which can attenuate IGF1R protein expression and PI3K/Akt signal pathway resulting in hyperglycemia." (PMID 29069833, 2017). "In the clinical trials of CO-1686 and AZD9291, hyperglycemia has been observed as one of the adverse events, possibly due to the activity against INSR and IGF1R kinases either through themselves or the corresponding metabolites." (PMID 28407693, 2017). "Using the 30% total body surface area (TBSA) model of burn injury in rats we found that the miRNA let-7b can target IGF1R and downregulate its protein expression, in turn attenuating PI3K/Akt and Gsk3β activation leading to hyperglycemia." (PMID 29069833, 2017). "For instance, due to the homology between IGF-1R and INSR, the inhibition of IGF-1R signaling disrupts INSR signaling and results in unwanted side effects, such as hyperglycemia and hyperinsulinemia." (PMID 24816813, 2014). "Since there is significant cross-talk between leptin receptor, insulin, and IGF1R/IGF1 (insulin-like growth factor) signaling pathways, we assessed the effect of hyperglycemia on key intermediates within each of these pathways." (PMID 24260287, 2013). "IGF-1R blockage has also been tested as a treatment for cancers, including HCC, but there were serious adverse events, including dehydration, asthenia, and hyperglycemia." (PMID 29113314, 2017). "Furthermore, it has been established that miR-194 can target insulin-like growth factor 1 receptor (IGF1R) and result in hyperglycemia post-burn injury." (PMID 29069833, 2017). "In conclusion, our data indicates that continuous hyperglycemia might lead to an elevated expression of Grb10 and the subsequent decrease in IGF-1/IGF-1R signaling in kidneys, which may consequently contribute to the pathogenesis of diabetic nephropathy." (PMID 26986757, 2016). "Given that hyperglycemia has been reported for both PI3K and IGF1R inhibitors, combination of the two may result in increased side effects." (PMID 27048245, 2016). "MKR mice, which possess a mutant dominant-negative insulin-like growth factor-1 receptor (KR-IGF-1R) specifically targeted to skeletal muscle, exhibit features of nonobese type 2 DM, such as hyperglycemia, dysinsulinemia and dyslipidemia, and reduced NCV, accompanied by hypoalgesia." (PMID 38089620, 2023). "Despite some cases showing exceptional responses, the majority of trials involving IGF-1R inhibitors have failed, due to factors including lack of predictive biomarkers, dose-limiting hyperglycaemia resulting from co-inhibition of INSR, and incomplete understanding of IGF-1R biology." (PMID 33969359, 2021). "Additionally, IGF1R blocking can induce hyperglycemia and hyperinsulinemia in patients, which could activate the IRA in response to IGF1R inhibition." (PMID 33260481, 2020). "In addition, considering that some of the EGFR inhibitors induced hyperglycemia in the clinic, which was possibly through inhibition of the INSR and IGF1R kinases, we also tested this drug in parallel with AZD9291 in the INSR and IGF1R transformed isogenic BaF3 cells." (PMID 28407693, 2017).
Hyperglycemia (continued). "Therefore, as expected, hyperglycemia enhances IGF1R/insulin receptor signaling in both non-tumorigenic and malignant breast epithelial cells." (PMID 24260287, 2013). "Up to 46% of patients developed grade 3-4 hyperglycemia, similar to what was seen in the phase II NSCLC study of CP-751871, thus raising the possibility that hyperglycemia could be the dose limiting toxicity of IGF-1R monoclonal antibodies." (PMID 21729319, 2011). "No patient developed hyperglycemia, suggesting that the insulin receptor is not a clinically significant target of AXL1717 in contradistinction to the IGF-1R inhibitor OSI-906 and the IGF-1R targeting monoclonal antibodies." (PMID 29113409, 2017). "Other important observations from this study include enhanced IGF1R signaling and increased AKT/mTOR activation under hyperglycemia in both non-tumorigenic and malignant breast epithelial cells." (PMID 24260287, 2013). "Secondly, the development of IGF neutralizing antibodies provides a means of blocking IGF-1R and INSR-A without compromising insulin signaling via INSR-B, thereby avoiding dose-limiting hyperglycemia that contributed to adverse outcomes in IGF-1R inhibitor trials." (PMID 31416218, 2019). "However, inhibition of IGF-1R directly is not applicable for prevention because of the potential side effects of small-molecule IGF-1R inhibitors, such as hyperglycemia due to cross-reactivity to the insulin receptor (IR)." (PMID 27708216, 2016). "However, despite some cases showing exceptional responses, the majority of IGF/IGF‐1R inhibitor trials failed due to factors including lack of predictive biomarkers, dose‐limiting hyperglycaemia resulting from INSR co‐inhibition, and incomplete understanding of IGF‐1R biology." (PMID 41028981, 2025).